UQCRH (ubiquinol-cytochrome c reductase hinge protein)
Description:
Component of the ubiquinol-cytochrome c oxidoreductase, a multisubunit transmembrane complex that is part of the mitochondrial electron transport chain which drives oxidative phosphorylation. The respiratory chain contains 3 multisubunit complexes succinate dehydrogenase (complex II, CII), ubiquinol-cytochrome c oxidoreductase (cytochrome b-c1 complex, complex III, CIII) and cytochrome c oxidase (complex IV, CIV), that cooperate to transfer electrons derived from NADH and succinate to molecular oxygen, creating an electrochemical gradient over the inner membrane that drives transmembrane transport and the ATP synthase. The cytochrome b-c1 complex catalyzes electron transfer from ubiquinol to cytochrome c, linking this redox reaction to translocation of protons across the mitochondrial inner membrane, with protons being carried across the membrane as hydrogens on the quinol. In the process called Q cycle, 2 protons are consumed from the matrix, 4 protons are released into the intermembrane space and 2 electrons are passed to cytochrome c.
Synonyms: QCR6; UQCR8; MC3DN11
Tractability: Small molecule: a structure with a bound ligand is known. Antibody: UniProt places it where antibodies can reach, with medium confidence. PROTAC: ubiquitination databases record sites on it; its protein half-life has been measured.
Gene: Protein-coding gene on chromosome 1 (46,300,900 to 46,316,796, forward strand). Ensembl gene ENSG00000173660.
Subcellular location: Mitochondrion inner membrane
Pathways (Reactome):
Metabolism: Complex III assembly; Respiratory electron transport
Gene Ontology:
Molecular function: protein binding; quinol-cytochrome-c reductase activity
Biological process: aerobic respiration; cellular respiration; mitochondrial electron transport, ubiquinol to cytochrome c; oxidative phosphorylation; proton transmembrane transport
Cellular component: mitochondrial inner membrane; mitochondrion; respiratory chain complex III; respiratory chain complex; membrane
Genetic constraint (gnomAD): Loss-of-function variants: 14 observed, 17.03 expected, observed/expected ratio (o/e) 0.82, 90% interval 0.54 to 1.28. The upper end of that interval is the gene's LOEUF score, 1.28, which puts it in group 5 of 6, group 1 being the genes least tolerant of losing a copy. Missense variants: 89 observed, 115.13 expected, observed/expected ratio (o/e) 0.77, 90% interval 0.65 to 0.92. Synonymous variants: 41 observed, 44.6 expected, observed/expected ratio (o/e) 0.92, 90% interval 0.71 to 1.19.
Gene-disease validity (ClinGen):
ClinGen rates the evidence that UQCRH causes each of these diseases.
mitochondrial disease (autosomal recessive): Limited.
Homologues: Orthologues: dog UQCRH (95% identical), chimpanzee UQCRH (92% identical), mouse Uqcrh (90% identical), rat Uqcrh (84% identical), zebrafish uqcrh (69% identical), Drosophila melanogaster UQCR-11L (37% identical), Drosophila melanogaster UQCR-11 (36% identical). Paralogues in human: UQCRHL (97% identical).
Diseases named in the same sentence as UQCRH in open-access papers:
UQCRH is named in the same sentence as 28 diseases in open-access papers, as found by Europe PMC text mining. Sharing a sentence is not in itself a finding about the gene and the disease. The quoted sentences say what the papers report.
breast carcinoma (4 papers, 2013 to 2023). "For module #35, while most of the genes locate on 1q34, many of the genes such as UQCRH, PSMB2, PPIH, and YBX1 are involved in RNA processing and have been identified with breast cancer in multiple studies." (PMID 30906311, 2019). "With the exception of UQCRH and LRP8, the expression levels of genes positively correlated with YBX1, such as CTPS1, FMNL2, CDC20, B3GNT5, MTHFD1L, and CDCA8, were significantly and positively correlated with the expression level of YBX1 in 13 breast cancer cell lines." (PMID 30647855, 2018).
ovarian carcinoma (4 papers, 2017 to 2022). A malignant neoplasm originating from the surface ovarian epithelium. "The group additionally demonstrated downregulation of UQCRH expression in limited number of breast and ovarian cancer cell lines through a mechanism of promoter inactivation via epigenetic methylation." (PMID 28332314, 2017). "Among them, we found decreased expression of UQCRH in clear cell carcinoma of ovarian cancer." (PMID 34133843, 2022).
cognitive decline (2 papers, 2021 to 2025). "Further machine learning analysis revealed that a combination of four decreased platelet proteins, that is, PHB, UQCRH, GP1BA, and FINC, was most promising for predicting cognitive decline in MCI and AD patients." (PMID 33942972, 2021). "Further PLS‐DA analysis plus machine learning revealed that a combination of decreased proteins PHB, UQCRH, GP1BA, and FINC in platelets could be promising in objectively predict the cognitive decline in MCI and AD patients." (PMID 33942972, 2021).
renal carcinoma (2 papers, 2022). A carcinoma arising from the epithelium of the renal parenchyma or the renal pelvis. "A study demonstrated that UQCRH expression was positively associated with survival in patients with renal cell carcinoma, suggesting that UQCRH may act as a tumor suppressor gene in renal cancer." (PMID 36105252, 2022). "DNMT3B‐induced methylation of ubiquinol cytochrome c reductase hinge protein (UQCRH) contributes to renal cancer progression." (PMID 34133843, 2022). "Since the introduction of UQCRH was shown to induce apoptotic cell death of certain types of cells, we investigated whether the UQCRH regulates the apoptosis of renal cancer cells." (PMID 34133843, 2022). "Decreased expression of UQCRH inhibits cyt c release from mitochondria, which may be important for anti‐apoptotic phenotype of renal cancer cells." (PMID 34133843, 2022).
viral infection (2 papers, 2024 to 2025). "Some of the upregulated proteins, including SPRK1, STX12, and UQCRH, have been reported to be relevant to viral infection and replication." (PMID 40920846, 2025).
breast tumors (1 paper, 2011). "Determination of Complex III subunit gene expression identified over expression and co-regulation of UQCRFS1 (encoding RISP protein) and UQCRH (encoding Hinge protein) in 6 out of 9 human breast tumors." (PMID 21901141, 2011). "A total of 8 out of 9 breast tumors show coordinate regulation of UQCRFS1 and UQCRH suggesting a common factor involved in transcriptional regulation of these two genes." (PMID 21901141, 2011).
clear-cell renal cell carcinoma (1 paper, 2025). "In clear-cell renal cell carcinoma, UQCRH is frequently silenced by promoter hypermethylation, with low expression correlating with advanced disease and poor survival, suggesting a tumor-suppressive role." (PMID 41157129, 2025).
hypoglycaemia (1 paper, 2021). "Of note, Bcs1l mice displayed hypoglycaemia as a common symptom, usually observed in humans with CIII defects, including the UQCRH variants characterised here." (PMID 34750991, 2021).
prostate adenocarcinoma (1 paper, 2022). "Moreover, for three of these proteins, NPM1NPM1, VCAN, and UQCRH, we were able to validate their relative increase in BCR+ compared to BCR- using prostate adenocarcinoma mRNA data in TCGA." (PMID 35954429, 2022).
prostate carcinoma (1 paper, 2022). A carcinoma that arises from epithelial cells of the prostate gland. "Notably, all seven proteins were significantly associated with progression in Prostate Cancer Transcriptome Atles (PCTA) and NPM1NPM1, UQCRH, and VCAN were further validated in The Cancer Genome Atlas (TCGA), where they were upregulated in BCR+/BCR-." (PMID 35954429, 2022).
tumor (8 papers, 2016 to 2025). "We found that overexpression of UQCRH in KMRC2 reprogrammed the metabolic activity at several levels and demonstrated the metabolically-linked tumor suppressive activity of UQCRH in at least some of the ccRCC cases." (PMID 32929120, 2020). "Silencing of UQCRH attenuated the cytochrome c release in response to apoptotic stimuli and resulted in enhancement of primary tumor formation in vivo, implying the tumor‐suppressive role of UQCRH." (PMID 34133843, 2022). "Our study demonstrates that UQCRH is a putative tumor suppressor gene for ccRCC, based on the effect of UQCRH overexpression on both in vitro metabolism assays as well as in vivo tumor growth." (PMID 32929120, 2020). "Subsequently, we examined the effect of UQCRH overexpression on KMRC2 subcutaneous tumor growth in immunodeficient mice." (PMID 32929120, 2020). "Thus, UQCRH appears to act as either a tumor suppressor or promoter depending on tissue context, yet in both cases, its expression levels serve as clinically relevant prognostic indicators." (PMID 41157129, 2025). "Consistent with the in vitro result, UQCRH overexpression slowed down the tumor growth in vivo." (PMID 32929120, 2020). "The inclusion of UQCRH, a subunit of the mitochondrial complex III, in our adverse prognostic signature is also notable, as it has been described as a tumor suppressor in some contexts." (PMID 41355397, 2025). "Both heterozygous and homozygous CNV analyses showed significant amplification for DCAF13 and FAM83D and deletion for FUCA2, UQCRH, and NDC80 in tumor samples." (PMID 41355397, 2025). "The gene expression profiles suggested that the expression levels of CDC20, UQCRH, TIMM10, TIMM13, POLR2L, and NDUFAB1 were upregulated in tumor tissue." (PMID 36901944, 2023). "UQCRH overexpression in KMRC2 induced higher apoptosis and slowed down in vitro and in vivo tumor growth." (PMID 32929120, 2020).
cancer (6 papers, 2011 to 2026). A tumor composed of atypical neoplastic, often pleomorphic cells that invade other tissues. "We determined if expression of UQCRFS1 (encoding RISP protein) and UQCRH (encoding Hinge) was also increased in other cancers." (PMID 21901141, 2011). "Although UQCRH is also involved in electron transport and the maturation of cytochrome c1, its role in cancer progression is controversial." (PMID 34133843, 2022). "Another subunit of Complex III, UQCRH, also displays context-dependent roles in cancer." (PMID 41157129, 2025). "Since UQCRH regulates the production of ROS, we hypothesized that UQCRH may be essential for the induction of apoptosis in cancer cells." (PMID 34133843, 2022). "We believe that increased UQCRH expression may be related to cancer cell proliferation because UQCRH was required in the early stage of DNA replication, along with other hinge protein members." (PMID 27358292, 2016). "Alternative splicing was pervasive, with recurrent high-magnitude events at cancer-relevant loci including GJA1 (SE), NF2 (A3/A5), LIN37 (A5), ECT2 (A3/A5), BCL2L11 (A3), UQCRH (A5), CSE1L (A3), BROX (A3), and multiple ZNFs." (PMID 41952686, 2026).
infection (2 papers, 2024 to 2025). The state of being infected such as from the introduction of a foreign agent such as serum, vaccine, antigenic substance or organism. "Serine/arginine-rich splicing factor protein kinase-1 (SRPK1), syntaxin 12 (STX12) and ubiquinol-cytochrome c reductase hinge protein (UQCRH) from the upregulated group have been reported to be related to the infection and replication of certain kinds of viruses." (PMID 40920846, 2025).
neurological disease (1 paper, 2021). "Functional analysis of these genes showed that UQCRH participates in cardiac muscle contraction, PPA2 is closely related to sudden cardiac failure (SCD), and OGT, as the interacting gene partner of PANO1, is associated with neurological disease." (PMID 34290742, 2021).
UQCRH also shares sentences with these, for which no sentence is quoted: hepatocellular carcinoma (3 papers); Parkinson disease (3); Alzheimer disease (2); COVID-19 (2); renal cell carcinoma (2); bacterial sepsis (1); clear cell carcinoma (1); epilepsy (1); neurodegenerative disease (1); ovarian tumor (1); paraganglioma (1); Parkinson’s (1); preeclampsia (1); Sepsis (1).